SOX8 (SRY-box transcription factor 8)
Description:
Transcription factor that may play a role in central nervous system, limb and facial development. May be involved in male sex determination. Binds the consensus motif 5'-[AT][AT]CAA[AT]G-3' (By similarity).
Tractability: PROTAC: ubiquitination databases record sites on it.
Gene: Protein-coding gene on chromosome 16 (981,444 to 986,979, forward strand). Ensembl gene ENSG00000005513.
Subcellular location: Nucleus
Subcellular location (Human Protein Atlas): Nucleoplasm
Gene Ontology:
Molecular function: sequence-specific double-stranded DNA binding; DNA binding; DNA-binding transcription factor activity, RNA polymerase II-specific; RNA polymerase II cis-regulatory region sequence-specific DNA binding; cis-regulatory region sequence-specific DNA binding; DNA-binding transcription factor activity; DNA-binding transcription factor binding; sequence-specific DNA binding
Biological process: positive regulation of transcription by RNA polymerase II; adipose tissue development; cell fate commitment; enteric nervous system development; fat cell differentiation; in utero embryonic development; male gonad development; metanephric nephron tubule formation; morphogenesis of a branching epithelium; morphogenesis of an epithelium; negative regulation of apoptotic process; negative regulation of DNA-templated transcription; negative regulation of myoblast differentiation; negative regulation of transcription by RNA polymerase II; neural crest cell development; neural crest cell migration; oligodendrocyte differentiation; osteoblast differentiation; peripheral nervous system development; positive regulation of branching involved in ureteric bud morphogenesis; positive regulation of DNA-templated transcription; positive regulation of gliogenesis; positive regulation of kidney development; positive regulation of osteoblast proliferation; regulation of hormone levels; and 7 more
Cellular component: nucleoplasm; nucleus; chromatin; cytoplasm; transcription regulator complex
Genetic constraint (gnomAD): Loss-of-function variants: 9 observed, 17.38 expected, observed/expected ratio (o/e) 0.52, 90% interval 0.31 to 0.9. The synonymous counts are far from expectation, so gnomAD's model fits this gene poorly and the ratio says little. Missense variants: 734 observed, 563.59 expected, observed/expected ratio (o/e) 1.3, 90% interval 1.23 to 1.38. Synonymous variants: 415 observed, 287.31 expected, observed/expected ratio (o/e) 1.44, 90% interval 1.33 to 1.57.
Homologues: Orthologues: chimpanzee SOX8 (99% identical), macaque SOX8 (97% identical), dog SOX8 (85% identical), mouse Sox8 (84% identical), pig SOX8 (83% identical), rat Sox8 (83% identical), guinea pig SOX8 (81% identical), tropical clawed frog sox8 (71% identical), zebrafish sox8a (53% identical), zebrafish sox8b (52% identical), Drosophila melanogaster Sox14 (18% identical), Drosophila melanogaster Sox21a (17% identical), and 3 more. Paralogues in human: SOX9 (52% identical), SOX10 (49% identical), SOX30 (23% identical), SOX17 (20% identical), SOX18 (19% identical), SOX5 (19% identical), CFAP65 (19% identical), SOX21 (19% identical), SOX6 (18% identical), SOX1 (18% identical), SOX11 (18% identical), SOX14 (18% identical), and 8 more.
Diseases named in the same sentence as SOX8 in open-access papers:
SOX8 is named in the same sentence as 65 diseases in open-access papers, as found by Europe PMC text mining. Sharing a sentence is not in itself a finding about the gene and the disease. The quoted sentences say what the papers report.
tongue squamous cell carcinoma (11 papers, 2019 to 2025). A squamous cell carcinoma that arises from the tongue. "In a clinical study, SOX8 is over-expressed in chemoresistant patients with tongue SCC and is associated with higher lymph node metastasis, advanced tumor stage and shorter overall survival." (PMID 34090518, 2021). "In the study on SOX8 in tongue squamous cell carcinoma, it was discovered that the knockout of this gene inhibited stem-like capacities, mesenchymal features and tumor metastasis in cancer chemoresistant cells." (PMID 38132438, 2023). "In support of this, investigations by Xie and colleagues confirmed that SOX8-mediated Wnt/β-catenin pathways gave rise to stem-like properties, cisplatin resistance and an epithelial-to-mesenchymal transition phenotype in tongue squamous cell carcinoma." (PMID 35477537, 2022). "For example, in tongue squamous cell carcinoma, Sox8 can combine with the FZD7 promoter region of the Wnt receptor and activate the Wnt/β-catenin signaling pathway regulated by FZD7, thus regulating tumor cell chemosensitivity, stem cell stemness and EMT." (PMID 30670025, 2019). "SOX8 promotes proliferation of tongue squamous cell carcinoma." (PMID 39889187, 2025). "Interaction between SRY-box transcription factor 8 (SOX8) and TFAP2A increases Golgi phosphoprotein 3 (GOLPH3) promoter activity and tumor growth of tongue squamous cell carcinoma." (PMID 37291585, 2023). "In tongue squamous cell carcinoma (TSCC), patients’ higher expression of SOX8 caused lymph node metastasis, chemotherapeutic resistance and a poor prognosis." (PMID 38132438, 2023). "SOX8 belongs to SOX group E, and it was shown to be overexpressed in various cancer types including triple-negative breast cancer (TNBC), ovarian cancer, and tongue squamous cell carcinoma, while promoting the tumorigenesis and progression of tumors." (PMID 36246971, 2022). "While SOX8 is known to regulate cancer stem-like properties and cisplatin-induced EMT in tongue squamous cell carcinoma through effects on the Wnt/β-catenin pathway 37, its functions and mechanisms of action in cancer, particularly ovarian cancer, have rarely been documented." (PMID 32550913, 2020).
hepatocellular carcinoma (9 papers, 2018 to 2024). A malignant tumor that arises from hepatocytes. "The SOX8 promotor is hypermethylated in cervical cancer and hepatocellular carcinoma." (PMID 38611002, 2024). "Interestingly, metastasizing hepatocellular carcinomas and squamous cell carcinomas show higher expression of SOX8 too25,26." (PMID 34997020, 2022). "In addition, SOX8, a marker for human hepatocellular carcinomas, was strongly upregulated in high-dose infection and had a smaller impact in lower-dose infections; in contrast, upregulation was more pronounced in the low-ISG cohort than in the high-ISG cohort." (PMID 35993785, 2022). "SOX8 overexpression triggers ferroptosis in hepatocellular carcinoma by disrupting glycolipid metabolism, redox balance, and iron homeostasis, suggesting a novel therapeutic strategy for HCC." (PMID 39315094, 2024). "SOX8 and SOX9 induced the FZD7-mediated activation of the WNT/β-catenin pathway to regulate chemoresistance, stem-like properties and EMT in tongue squamous cell carcinoma (TSCC) and hepatocellular carcinoma (HCC)." (PMID 29789460, 2018).
male infertility (6 papers, 2018 to 2025). The inability of the male to effect fertilization of an ovum after a specified period of unprotected intercourse. "Although, a contribution of Sox8 to male infertility in the mouse has been establishedfor some time, the finding of an association between human POI and SOX8 variants is anovel finding since Sox8−/− female miceare fertile." (PMID 29373757, 2018). "As shown by numerous studies, deletion of Sox8 results in adult male infertility." (PMID 39936824, 2025). "Additionally, impaired Sox8 function in the maintenance of Sertoli cells and the BTB causes severe dysregulation of spermatogenesis with consequent male infertility." (PMID 39936824, 2025). "They found that male infertility and a variety of abnormalities, including 46, XY DSD (disorder in sex development) and 46, XX POI (primary ovarian insufficiency), are caused by mutations in the Sox8 gene." (PMID 37508024, 2023). "These cases of male infertility may represent mild forms oftesticular dysgenesis or, similar to the mouse model the SOX8 protein may also be aregulator of Sertoli–germ cell adhesion independently of its role in primarytestis-determination." (PMID 29373757, 2018). "In 2018, two rearrangements involving the SOX8 locus and one missense heterozygous variant in SOX8 (c.468G>C; p.Glu156Asp) were identified in 46,XY DSD patients, and other missense variants were associated with male infertility and ovarian insufficiency in females." (PMID 32224856, 2020).
multiple sclerosis (6 papers, 2021 to 2025). A progressive autoimmune disorder affecting the central nervous system resulting in demyelination. "For instance, genetic variants of SOX8 have been linked to multiple sclerosis and familial essential tremor, while SOX8 alterations have been related to poor cancer prognosis and infertility." (PMID 39936824, 2025). "This is further supported by the association of SOX8 mutations with several human diseases that result in neurological symptoms, as discussed more in detail in the section, ‘Implications of Sox8 in Multiple Sclerosis and other diseases’." (PMID 39936824, 2025). "Genome-wide association studies identified a single nucleotide polymorphism (SNP) downstream of the transcription factor Sox8, associated with an increased risk of multiple sclerosis (MS)." (PMID 38097655, 2023). "Additionally, we would like to point out that SOX8 is a known genetic risk locus for multiple sclerosis." (PMID 39201442, 2024). "Additionally, SOX8 has been identified as genetic risk loci for Multiple Sclerosis in humans." (PMID 33867936, 2021). "Thus, TFs as SOX8, implicated in OLG development and MS susceptibility, might work in concert with TFs other than the ones they usually cooperate with during development and homeostasis, in order to regulate immune gene transcription in OLG in EAE/MS." (PMID 35093191, 2022).
ovarian carcinoma (6 papers, 2020 to 2024). A malignant neoplasm originating from the surface ovarian epithelium. "While SOX10’s involvement in ovarian carcinomas was assessed, other common expression markers studied for ovarian cancer include SOX8 and, notably, SOX9, which has been implicated in various signaling pathways in ovarian cancer development." (PMID 38132479, 2023). "Aurora-A, a member of the Aurora kinase family, regulates glucose metabolism in ovarian cancer via the SOX8/FOXK1 signaling axis and induces cisplatin resistance." (PMID 34496868, 2021). "Overall, 75.68% (140/185) chemoresistant ovarian cancer tissues showed high expression of SOX8 relative to 53.25% (131/246) chemosensitive ovarian cancer tissues." (PMID 32550913, 2020). "High Aurora-A (log-rank P = 0.0007), SOX8 (log-rank P <0.0001), and FOXK1 (log-rank P = 0.0050) levels were associated with poor OS in chemosensitive ovarian cancer." (PMID 32550913, 2020). "A recent study showed that Aurora-A mediates glucose metabolism via SOX8/FOXK1 in ovarian cancer." (PMID 33867847, 2021). "Our data suggest that SOX8 is a potential target of Aurora-A in ovarian cancer." (PMID 32550913, 2020). "In a study, the researchers utilized the organoid model of ovarian cancer to validate the hypothesis that abnormally overexpressed serine/threonine kinase Aurora-A directly phosphorylates sex-determining region Y-box 8 (SOX8) at Ser327 or indirectly enhances SOX8 transcription via c-Myc." (PMID 37681030, 2023). "Our results showed that SOX8 targets FOXK1, thereby regulating its transcription, which has significant impacts on senescence, glycolysis and chemoresistance in ovarian cancer." (PMID 32550913, 2020). "In summary, the Aurora-A/SOX8/FOXK1 signaling axis promotes chemoresistance via suppression of cell senescence and induction of glucose metabolism in ovarian cancer organoids and cells." (PMID 32550913, 2020). "To determine the clinical significance of Aurora-A, SOX8, and FOXK1 in ovarian cancer, we assessed their expression patterns using cisplatin-sensitive and -resistant ovarian cancer tissue microarrays (n = 246 and 185, respectively)." (PMID 32550913, 2020). "Thus, the AURKA/SOX8/FOXK1 signaling axis promotes chemoresistance by suppressing cell senescence and inducing glucose metabolism in ovarian cancer." (PMID 39334449, 2024). "Similarly, high Aurora-A, SOX8, and FOXK1 expression was correlated with poor OS in chemoresistant ovarian cancer (P = 0.0035, 0.0001, and 0.0003, respectively)." (PMID 32550913, 2020). "Moreover, Aurora-A appears to exert a regulatory role through direct binding and phosphorylation of the transcription factor SOX8 to activate the SOX8/FOXK1 signaling axis, highlighting this pathway as a novel potential therapeutic target for chemoresistant ovarian cancer." (PMID 32550913, 2020).
breast carcinoma (4 papers, 2013 to 2024). "In breast cancer patients, amplification of SOX8 caused poor overall survival." (PMID 38132438, 2023). "SOX8 is also found to be a signature of basal-like immune-suppressed triple-negative breast cancer; amplification of SOX8 significantly shortens the survival of patients with breast cancer." (PMID 32411596, 2020).
glioma (4 papers, 2014 to 2024). A benign or malignant brain and spinal cord tumor that arises from glial cells (astrocytes, oligodendrocytes, ependymal cells). "SOX8 is differentially expressed in primary gliomas, being upregulated in oligodendrogliomas and low-grade astrocytomas, but downregulated in glioblastomas, compared to healthy adult brain." (PMID 38611002, 2024). "In contrast, key regulators of OPC specification and maintenance, including MYT1, OLIG2, PDGFRA, PTPRZ1, SMOC1, and SOX8 were hypomethylated in PM gliomas." (PMID 37055795, 2023). "In the unique module identified by DiME from the GBM glioma network, the RRAS oncogene, the SH3 domain binding kinase gene SBK1 and the transcription factor SOX8 involved in CNS development have the highest degrees of connectivity." (PMID 24523864, 2014).
Infertility (4 papers, 2013 to 2025). "In summary, SOX8 has emerged as a gene of interest in several pathologies, often associated with infertility, muscle, skeletal, and neurological deficits." (PMID 39936824, 2025). "Several case studies in humans have linked mutations of SOX8 with infertility or reproductive disorders." (PMID 39936824, 2025). "In addition to developmental regulation, Sox8 plays an important role in the maintenance of tissue homeostasis, as evidenced by the phenotype of adult Sox8-deficient mice, which exhibit osteopenia, reduced weight, infertility, and poor recovery in demyelinating models." (PMID 39936824, 2025). "We found copy number differences in infertile dogs compared with fertile for genomic regions encompassing TEKT1, DNM2 and SOX8 genes, suggesting a role in infertility biology if deleted or duplicated with respect to reference copy number." (PMID 24373333, 2013). "In the same study, Sox8 null mice developed a severe infertility phenotype, with spermiation failure and impairment of spermatogenic cycle." (PMID 24373333, 2013). "Additionally, it discusses Sox8's implications in various pathological processes, such as cancer, infertility, and other diseases, as well as its potential as a therapeutic target." (PMID 39936824, 2025). "Inferring precisely howthese mutations cause infertility is difficult since the gene regulatory pathways downstreamof SOX8 have not been defined in either the XY or XX gonad." (PMID 29373757, 2018). "To investigate whether mutations in SOX8, like NR5A1,could also contribute to a wider spectrum of male and female infertility, we sequenced thecoding region of SOX8 in 427 men and women with infertility." (PMID 29373757, 2018). "Sox8 homozygous null males show no embryonic or early postnatal phenotypes, including in the gonad, but seminiferous tubule failure and infertility develop at around 5 months." (PMID 28045957, 2017).
osteoarthritis (4 papers, 2021 to 2023). A noninflammatory degenerative joint disease occurring chiefly in older persons, characterized by degeneration of the articular cartilage, hypertrophy of bone at the margins and changes in the synovial membrane. "Collectively, the present study indicates that Sox8 downregulation inhibits the PI3K/AKT/mTOR signaling pathway and increases the level of autophagy in MSU-induced impairment of chondrocytes in vitro and in vivo, making Sox8 a potential treatment target for gout-induced osteoarthritis." (PMID 36918540, 2023).
astrocytomas (3 papers, 2014 to 2024). "PDGFRA and SOX8 were clearly more associated with OLIG1+ cells in both the oligodendroglioma and the astrocytoma." (PMID 33925547, 2021). "SOX8 has been shown to be predominantly expressed in oligodendrocytomas, astrocytomas and glioblastomas and may be an early glial marker for medulloblastomas." (PMID 24523864, 2014).
colorectal cancer (3 papers, 2023 to 2024). A primary or metastatic malignant neoplasm that affects the colon or rectum. "Similarly, USP29 upregulation mediates KIAA1429 deubiquitination, thereby stabilizing SOX8 mRNA and protein levels through m6A modification to facilitate malignant proliferation in colorectal carcinoma (CRC)." (PMID 37391814, 2023).
glioblastoma (3 papers, 2014 to 2024). The most malignant astrocytic tumor (WHO grade IV). "Meanwhile, SOX8 had a lower H3K27ac signal in the MES-like GBM, suggesting that SOX8 may be a potential target for epigenetic control and subtype gene regulatory remodelling in glioblastoma." (PMID 39629136, 2024).
Intellectual disability (3 papers, 2013 to 2023). "These sites were screened through Geno2MP medical phenotypes, revealing novel SOX15 R104G associated with musculature abnormality and SOX8 R159G with intellectual disability." (PMID 36672963, 2023). "For example, the Dizeez-generated and manually-validated associations between SOX8 and mental retardation and between NBPF3 and Neuroblastoma are not present in the DGA." (PMID 23951102, 2013). "SOX8 R159G (HMG box location 58/60) was absent in gnomAD and present in two individuals of Geno2MP with intellectual disability and microcephaly." (PMID 36672963, 2023).
prostate carcinoma (3 papers, 2022 to 2025). A carcinoma that arises from epithelial cells of the prostate gland. "Notably, SOX8‐induced ferroptosis is particularly effective against prostate cancer cells with high lipid demands." (PMID 40159622, 2025). "Furthermore, two PSA-dependent prostate cancer risk scores were developed (PRISK1 and PRISK2) which combine known PCa risk factors QfPSA, patient’s age, and the amount of plasma cfDNA with methylated RASSF1A, MIR129-2, NRIP3, and SOX8 cfDNA sequences/mL." (PMID 38611002, 2024).
triple-negative breast carcinoma (3 papers, 2020 to 2023). An invasive breast carcinoma which is negative for expression of estrogen receptor (ER), progesterone receptor (PR), and human epidermal growth factor receptor 2 (HER2). "SOX8 is considered a detrimental prognostic factor for triple-negative breast cancer and tongue squamous cell cancer." (PMID 36373629, 2023). "SOX8 is up-regulated in low immune score samples that has a significant effect on cell migration and apoptosis in triple negative breast cancer, and is involved in the maintenance to stem-like capacities in cancer cells." (PMID 36869083, 2023).
alveolar rhabdomyosarcoma (2 papers, 2023). A rapidly growing malignant mesenchymal neoplasm. "In alveolar rhabdomyosarcoma, the chimeric transcription factor PAX3-FOXO1 interacts with the master transcription factors MYCN, MYOG and BRD4 at target gene super-enhancers, resulting in over-expression of SOX8, MYOD1, MYOG and MYCN, alveolar rhabdomyosarcoma tumorigenesis and dependence on BRD4." (PMID 38135679, 2023).
female infertility (2 papers, 2018 to 2023). Diminished or absent ability of a female to achieve conception. "In this study, we have also identified mutations in SOX8 associated withcases of male and female infertility." (PMID 29373757, 2018). "We therefore sought toexamine the profile of SOX8 expression in the human ovary to see if this is consistentwith a role for mutations in the protein contributing to female infertility." (PMID 29373757, 2018). "Heterozygous missense variants in SOX8 are associated with either male or female infertility." (PMID 36631813, 2023).